QSOX1 (quiescin sulfhydryl oxidase 1)
Diseases named in the same sentence as QSOX1 in open-access papers (continued):
Sharing a sentence is not in itself a finding about the gene and the disease.
endometriosis (1 paper, 2025). The growth of functional endometrial tissue in anatomic sites outside the uterine body. "Subsequently, by the intersection analysis, we obtained four overlapping genes (PMP22, QSOX1, REV3L, SP110) as potential co-diagnostic genes for SLE and endometriosis." (PMID 39744159, 2025). "Subsequently, by LASSO regression analysis, we constructed prediction models for 15 diagnostic genes in the endometriosis cohort and 6 diagnostic genes in the SLE cohort, respectively, and identified four co-diagnostic genes (PMP22, QSOX1, REV3L, SP110)." (PMID 39744159, 2025). "Collectively, PMP22, QSOX1, REV3L, SP110 may serve as potential diagnostic biomarkers for early diagnosis and targeted therapy of endometriosis and SLE." (PMID 39744159, 2025). "The expression of four potential co-diagnostic genes in the endometriosis validation cohort (GSE31515 and GSE87909) showed that the expression of QSOX1 and SP110 were significantly upregulated in the endometriosis group than normal group, which were consistent with the training group." (PMID 39744159, 2025). "Our study showed that QSOX1 was significantly upregulated in both endometriosis patients and SLE patients, which may be responsible for excessive oxidative stress in chronic inflammation and immunological disorders." (PMID 39744159, 2025). "Four co-diagnostic genes (PMP22, QSOX1, REV3L, SP110) were identified for endometriosis and SLE." (PMID 39744159, 2025). "The expression of PMP22, QSOX1 and SP110 were significantly higher in the ovarian endometriotic tissues from endometriosis patients compared to normal endometrial." (PMID 39744159, 2025).
heart failure (1 paper, 2024). Inability of the heart to pump blood at an adequate rate to meet tissue metabolic requirements. "The expression of proteins involved in Ig-mediated immune activation [e.g., Fc Gamma Receptor IIIa FCGR3A], proteins associated with heart failure [e.g., Tenascin C (TNC), Quiescin sulfhydryl oxidase 1 (QSOX1)], was enhanced in severe MIS-C compared to KD." (PMID 39457139, 2024).
Hypertension (1 paper, 2023). The presence of chronic increased pressure in the systemic arterial system. "Still, an increased expression of SVEP1, NRP1, RNASE1, QSOX1, and GKN1, along with decreased expression of XYLT2, CFH, LEP, and CETP serum levels were found in patients with hypertension." (PMID 37792298, 2023).
infertile (1 paper, 2022). "The expression of LCP1, CTSH, BPIFB1 and Quiescin sulfhydryl oxidase 1 (QSOX1) is significantly higher in infertile receptive phase uterine lavage compared to fertile." (PMID 36589798, 2022).
medulloblastoma (1 paper, 2015). A malignant, invasive embryonal neoplasm arising from the cerebellum. "QSOX1 is detected in human cerebellar tissue and medulloblastoma samples; however, determining expression of this enzyme does not help in the identification of risk groups as it does not appear to be associated with a worse prognosis." (PMID 25908093, 2015). "In view of this, as medulloblastomas are made up of embryonic cells and maturation may be related to a better prognosis for these tumors, expression of QSOX1 in medulloblastomas would be expected to be related to better biological behavior." (PMID 25908093, 2015).
pancreatic ductal adenocarcinoma (1 paper, 2013). An infiltrating adenocarcinoma that arises from the epithelial cells of the pancreas. "QSOX1 protein was reported by our laboratory to be over-expressed in tumors from patients diagnosed with pancreatic ductal adenocarcinoma (PDA)." (PMID 23536962, 2013).
Rectal prolapse (1 paper, 2023). Protrusion of the rectal mucous membrane through the anus. "QSOX1 KO mice did not display the growth retardation, occult blood loss, and rectal prolapse exhibited by mice lacking Muc2, the major intestinal gel‐forming mucin." (PMID 36245281, 2023).
tumor (33 papers, 2008 to 2025). "QSOX1 expression is associated with tumor cell invasion, tumor grading, and abnormal extracellular matrix protein deposition." (PMID 40822284, 2025). "The overexpression of QSOX1 has been associated with a higher tumor grade, increased cell proliferation, increased cell invasion, and poor prognosis." (PMID 39518060, 2024). "In line with in vitro results, QSOX1 knockdown caused a lower rate of tumor formation and reduced tumor burden in gefitinib-resistant subcutaneous xenograft models." (PMID 37161388, 2023). "In the current SCLC cohort, downregulation of the inflammation marker (IGKV4-1), the tumor aggressivity associated marker (QSOX1), and the tumor suppressor marker (TGFβ1) were observed." (PMID 34996345, 2022). "Accumulating evidence has revealed that intracellular QSOX1 acts as a tumor suppressor in HCC cells, whereas extracellular QSOX1 functions as a tumor promoter." (PMID 39857439, 2025). "QSOX1, another PAS marker revealed here, has also been implicated in tumor cell invasion, through activation of MMP-2 and MMP-922." (PMID 36604494, 2023). "Inhibition of extracellular QSOX1 using monoclonal antibody inhibitors was found to slow tumor growth and decrease metastasis, apparently by modulating ECM properties rather than Golgi redox state." (PMID 36245281, 2023). "All six proteins are differentially expressed in malignant vs. healthy tissue in CRC (FBLN1, MMP3, ACTN4, THBS1, EDIL3) or other tumour entities (QSOX1)." (PMID 33802764, 2021). "These proteins (THBS1, FBLN1, EDIL3, QSOX1, ACTN4, MMP3) also displayed differential mRNA expression in CRC compared to healthy intestine in the CRC TCGA dataset, and are implicated in tumour growth and metastasis regulation." (PMID 33802764, 2021). "To gain insight into the mechanism by which QSOX1 inhibitory antibodies interfere with tumor progression in vivo, we examined the microenvironment of 4T1 tumors from control and antibody-treated mice." (PMID 32064042, 2020). "A general consensus is emerging that QSOX1 overexpression is important during tumor cell invasion, facilitating tumor cell migration at the tumor‐stroma interface." (PMID 32536039, 2020). "Focusing on the contribution of extracellular QSOX1 to the tumor microenvironment by specifically targeting the secreted enzyme is an alternative method to counter the participation of QSOX1 in adenocarcinomas." (PMID 32064042, 2020). "Based on our finding that secreted QSOX1 contributes to tumor cell migration in cell cultures, we examined the effect of extracellular QSOX1 inhibition on metastasis." (PMID 32064042, 2020). "QSOX1 has been found to be over-expressed in multiple types of cancers, however, controversy exists regarding the action of QSOX1 as a tumor suppressor or promoter." (PMID 30962950, 2019). "QSOX1, SOX2, SLUG, STF1 were all associated to a more benign course of disease, suggesting control of tumor initiation and cancer stem-cell functions versus epithelial-mesenchimal transition in NSCLC." (PMID 30473748, 2018). "QSOX1 is a key enzyme involved in the ability of tumor cells to modify the ECM, and QSOX1 inhibition can undermine cell migration." (PMID 29423042, 2018). "Quiescin sulfhydryl oxidase 1 (QSOX1) is a highly conserved disulfide bond-generating enzyme that is overexpressed in diverse tumor types." (PMID 26158899, 2015). "Here we report that QSOX1 expression contributes to tumor growth in an in vivo pancreatic tumor cell xenograft model, supporting QSOX1 as a potential molecular therapeutic target." (PMID 26158899, 2015). "QSOX1 is an emerging target in tumor biology given its roles in cell growth, invasion, and the regulation of extracellular matrix composition." (PMID 26158899, 2015). "Here we establish that QSOX1 promotes tumor growth in vivo, strengthening the connection between elevated QSOX1 expression and tumor aggression." (PMID 26158899, 2015).
tumor (continued). "An inhibitory antibody recently developed blocks QSOX1 activity and reduces the invasion of tumor cells across a fibroblast monolayer, supporting the idea that directly targeting QSOX1 enzyme activity has anti-invasive properties." (PMID 26158899, 2015). "We have provided evidence that inhibition of QSOX1 activity by ebselen leads to significantly decreased invasion of tumor cell lines in vitro and reduced tumor growth in vitro and in vivo, effects comparable to QSOX1 knockdown." (PMID 26158899, 2015). "Recently, Soloviev and colleagues have demonstrated that QSOX1 mRNA is overexpressed in breast ductal carcinoma and that this increase is correlated to the tumor grade." (PMID 24475161, 2014). "To begin to assess the mechanistic role that QSOX1 plays in tumor cells we stably knocked-down QSOX1 expression in MCF7, BT549 and BT474 cells using two lentiviral shRNA constructs, sh742 and sh528." (PMID 23536962, 2013). "Addition of exogenous recombinant QSOX1 protein to shQSOX1 transduced tumor cells rescued their invasive properties, confirming previous data suggesting that QSOX1 is secreted into the extracellular matrix." (PMID 23536962, 2013). "QSOX1 transcription was elevated in an increasing proportion in the grade 2 and grade 3 tumours (graded according to the Nottingham prognostic index), with 10 of the 15 grade 3 tumours (67%) examined exceeding the normal range." (PMID 23460839, 2013). "The overexpression of QSOX1 in different types of tumours, and the ability to detect the protein or its fragments in body fluids including plasma, and urine makes QSOX1 a promising target for studying as a candidate universal prognostic cancer marker gene." (PMID 23460839, 2013). "Thus, we investigated the roles of QSOX1 in GBM cell behavior in vitro and in vivo using our embryonic chick brain orthotopic tumor model and have implicated its importance in the invasion of brain tissue." (PMID 39518060, 2024). "Furthermore, Dcn, Cav1, Cdkn1a, Myc, Qsox1, and Pdgfr-b are known for their role in promoting tumor-cell aggressiveness, EMT and sustaining the proliferation of mesenchymal cells." (PMID 34775465, 2021). "Enhanced QSOX1 transcription was found in 4T1 cells removed from lung metastases, compared to cells from the main tumor, suggesting that QSOX1 may be involved in the dissemination and infiltration of 4T1 tumors." (PMID 32064042, 2020). "Since ebselen inhibits QSOX1, we hypothesized that it would suppress invasion of tumor cells similar to shRNA-mediated knockdown of QSOX1." (PMID 26158899, 2015). "Therefore, it is now clear that the role of QSOX1 in cancer is complex mainly because of the existence of its different transcripts and that its function seems to depend on the stage and type of tumor." (PMID 24475161, 2014). "As such, we wondered whether the involvement of QSOX1 in autophagy might explain its function in tumor progression." (PMID 24475161, 2014). "Since autophagy is a stress-regulated mechanism involved in cancer progression, we investigated whether QSOX1 could regulate the autophagic pathway, a regulation that could explain its role during tumor development." (PMID 24475161, 2014). "This developmental data combined with our results indicating that QSOX1 expression facilitates degradation of basement membranes suggests that tumor cells over-express QSOX1 to allow them to break down basement membranes and invade into adjacent tissues or into circulation." (PMID 23536962, 2013). "Moreover, we investigated QSOX1's potential role in regulating tumor growth and metastasis using cellular models in which we overexpressed or extinguished QSOX1 and xenograft experiments." (PMID 23098186, 2012). "All these results suggested that QSOX1 role on proliferation and cell cycle could be cell type or tumor stage dependent." (PMID 23098186, 2012).
tumor (continued). "In contrast, QSOX1 inhibition has a more specific effect on tumor-associated fibroblasts and may alter the quality and properties of the matrix without destroying protective functions of the tumor stroma." (PMID 32064042, 2020). "Suppression of QSOX1 expression in BT474 cells leads to an 85% reduction in invasion of both sh742 and sh528 transduced tumor cells." (PMID 23536962, 2013). "Inhibiting extracellular QSOX1 activity by antibody blockade significantly disrupted the ECM structure, thereby reducing cancer cell adhesion, invasion, or migration in vitro and suppressing tumor growth and metastasis in vivo." (PMID 39857439, 2025). "To summarise, we were able to identify activation status-related proteins in fibroblast-derived EXOs by using mass spectrometry and validated three of the four selected candidate proteins (QSOX1, THBS1 and EDIL3) related to malignant transformation and tumour progression." (PMID 33802764, 2021). "It has been shown that QSOX1 is a key enzyme in the ability of tumors to modify the ECM, which enables tumors to communicate with and/or modify their environment at the tumor-stroma interface, contributing to the invasion and subsequent growth of the tumor." (PMID 34350181, 2021). "From these results, it can be inferred that QSOX1 might not be involved in cancer initiation but does contribute to cancer progression, such as tumor invasion and metastasis." (PMID 30336636, 2018). "As QSOX1 secreted from fibroblasts is likely to have been washed from the tissue sections during sample processing, this staining may not represent the totality of QSOX1 enzyme in the tumor vicinity." (PMID 32064042, 2020). "Our results show that the QSOX1 transcript was significantly elevated in ductal tumours, but since this classification also included all tumours of advanced grade, the patient sample set we studied does not enable us to disentangle the effects of tumour classification versus tumour grade." (PMID 23460839, 2013). "Notably from these data we can project that targeting QSOX1 irrespective of tumor subtype could help to slow tumor cell proliferation as well as tumor cell invasion." (PMID 23536962, 2013). "Treatment of non-quiescent fibroblasts with TGF-β, a key regulator of tumor microenvironment signaling pathways and a driver of fibrotic ECM deposition, was previously shown to induce QSOX1 transcription." (PMID 32064042, 2020).
cancer (30 papers, 2010 to 2026). A tumor composed of atypical neoplastic, often pleomorphic cells that invade other tissues. "The overexpression of QSOX1 previously has been associated with highly invasive pancreatic, breast, and prostate cancers." (PMID 39518060, 2024). "It remains to be determined whether the increase in sialylation in cancer is linked to increased Golgi QSOX1, and whether this pathway would also be a valuable target for inhibition." (PMID 36245281, 2023). "Indeed, expression of QSOX1 spliced variants present differential expression patterns depending on the type of cancer and the specific role of these different transcripts remain elusive." (PMID 24475161, 2014). "More recently, QSOX1 has been associated to cancer and protection against cellular stress." (PMID 24475161, 2014). "Growing evidence demonstrates that QSOX1 is upregulated in multiple cancer types and influences key behaviors of cancer cells, including proliferation, migration, invasion, and metastasis." (PMID 41595257, 2026). "In this review, we summarize current knowledge of QSOX1 expression and regulation in cancer, discuss its functional roles, and highlight key unanswered questions to warrant further investigation." (PMID 41595257, 2026). "The involvement of QSOX1 in cancer progression hopefully will lead to the discovery of key proteins that can be targeted for therapeutic intervention or to targeting the function of QSOX1 itself." (PMID 39518060, 2024). "QSOX1 has been reported to be upregulated in a number of cancers, and the overexpression of QSOX1 has been correlated with aggressive cancers and poor patient prognosis." (PMID 39518060, 2024). "This decreased cell proliferation as a result of QSOX1 knockdown is in agreement with previous studies on pancreatic and breast cancers." (PMID 39518060, 2024). "Our experiments presented here add to the knowledge that supports an important role for QSOX1 in the progression of cancer and, specifically, GBM cancer." (PMID 39518060, 2024). "In many cases, ST expression levels increase in cancer, but it is possible that these enzymes are also activated post‐translationally, since increased QSOX1 expression is seen in many cancer types." (PMID 36245281, 2023). "QSOX1 is highly expressed in a variety of cancer tissues and studies have pointed to QSOX1 as a potential oncogene in HCC." (PMID 36052168, 2022). "The vertebrate ortholog of Qsox1, the protein with the largest changes in T antigen in the mrva mutant, can enhance cancer cell invasion in in vitro assays and higher levels of the protein have been associated with poor patient outcomes." (PMID 30910009, 2019). "Recently, several studies have shown that the expression of QSOX1 is dysregulated in cancer cells and that QSOX1 is involved in tumorigenesis." (PMID 29423042, 2018). "In fact, several studies have shown a deregulation of QSOX1 expression in cancer cells and its involvement in tumorigenesis." (PMID 24475161, 2014). "QSOX1 expression is deregulated in cancer cells and this protein has been described to be involved in tumorigenesis." (PMID 24475161, 2014). "We also observed that one atypical excreted disulfide oxidase quiescin sulfhydryl oxidase 1 (QSOX1), which supports cell-matrix adhesion and cell migration, is markedly overexpressed in cancer." (PMID 25243088, 2014). "Since QSOX1 is a key factor that drives cell proliferation, invasion, and poor prognosis in a variety of aggressive cancers, QSOX1 could play a similar important role in GBM tumorigenesis and cell invasion into human brain tissue." (PMID 39518060, 2024). "In addition, LLC mouse models with QSOX1 knock-down also proved that QSOX1 functions in promoting cancer metastasis." (PMID 30336636, 2018). "Several previous studies have shown an involvement of QSOX1 in cancer." (PMID 24475161, 2014).